VIM (vimentin)
Diseases named in the same sentence as VIM in open-access papers (continued):
Sharing a sentence is not in itself a finding about the gene and the disease.
cancer (continued). "FMRP binds mRNAs involved in epithelial mesenchymal transition (EMT) and invasion including E-cadherin and Vimentin mRNAs, hallmarks of EMT and cancer progression." (PMID 24092663, 2013). "A cadherin switch (from E-cadherin to N-cadherin) and the mesenchymal marker Vimentin have been reported to correlate strongly with EMT and convert cancer cells into invasive phenotype." (PMID 24349446, 2013). "Cell migration occurs in the course of development of different tissues and in several diseases including cancer and fibrosis by inducing the expression of α-SMA and vimentin." (PMID 22693547, 2012). "Positive immunohistochemical staining for VIM and S100A4 in cancer cells was observed in the cytoplasm, and a combination of the nucleus and cytoplasm." (PMID 22761930, 2012). "SB-431542 treatment decreased dose-dependently vimentin expression in Colo320 and HT29NRP2 cancer cells and even restored E-Cadherin levels in HT29NRP2 underlying that TGFRI plays an essential role in the maintenance of the EMT phenotype conferred by NRP2." (PMID 21747928, 2011). "Cancers undergoing EMT display cell intermediate filament status changes from a keratin rich network connected to adherens junctions and hemidesmosomes to a vimentin base connecting a focal adhesion." (PMID 21713035, 2011). "The cytokeratins belong to the type I and II of the IF's, desmin and vimentin belong to the type III and lamin to type V. This group of proteins have been widely used as markers of different cancers." (PMID 21711556, 2011). "More recently, vimentin has been regarded as mesenchymal cell marker in cancer-related EMT; drugs that target cancer cell growth also induce vimentin degradation in cancer cells." (PMID 21347296, 2011). "Amongst these genes we wanted to emphasize the differential expression of the gene coding for vimentin (VIM), an intermediate filament of the mesenchymal lineage involved in migration, cell signalling, cancer and neurological disease." (PMID 20735813, 2010). "On the other hand, all patients with cancers showing positive expression of both myosin IIA and vimentin suffered disease recurrence." (PMID 18212748, 2008). "Epithelial Mesenchymal Transition (EMT) was another pathway depleted upon knockout, and subsequent analysis revealed a significant correlation between NNMT and EMT-related genes (VIM, CDH2, FN1, TGFB1, and ZEB2) in both the Cancer Cell Line Encyclopedia (CCLE) panel and patient data." (PMID 41997904, 2026). "Since vimentin, a stromal intermediate filament protein is highly expressed during EMT, antibodies against cell-surface vimentin (CSV), a cancer-specific antigen, have been used to detect live CTCs in patients with EMT-associated carcinoma or malignant sarcomas." (PMID 40565003, 2025). "LIFU has been shown to decrease vimentin expression, reversing the EMT process which could be indicative of halting or slowing cancer progression." (PMID 39976192, 2025). "First, we noted that CDS1-high cancer cells express high levels of the epithelial marker gene E-cadherin (CDH1), whereas CDS1-low cancer cell lines express mesenchymal markers like ZEB1, ZEB2 and vimentin (VIM) 48,49." (PMID 40615674, 2025). "Following the same protocol as the immunofluorescence of cancer cells, RAW-Blue macrophages were treated with either TGFβ-1 (4.0 × 10−3 μg/mL), IL-6 (4.1 × 10−5 μg/mL), or HGF (5.97 × 10−4 μg/mL) and stained with E-cadherin, N-cadherin, and vimentin." (PMID 40227834, 2025). "PTMs of tight junction proteins, including epithelial cell adhesion molecule (EpCAM) and claudins, cytoskeletal proteins (vimentin, actins, and tubulins), HIF1α, EMT-TFs, and matrisome proteins (collagen, fibronectin, and metalloproteinases) modulate invasion and metastasis of cancer." (PMID 39860065, 2025). "Understanding the proteomic landscape of vimentin-positive EVs opens avenues for targeted therapeutic strategies aimed at modulating EMT in pathological conditions such as wound healing, fibrosis, and cancer metastasis." (PMID 40618999, 2025).
cancer (continued). "In addition, we examined the expression levels of epithelial‐mesenchymal transition (EMT) markers including E‐cadherin, N‐cadherin, vimentin, and Snail in MDA‐MB‐231 cells, as these markers are known to be responsible for cancer stem cell properties." (PMID 40059964, 2025). "Vimentin is a mesenchymal cell marker and is not a fibroblast specific marker, as it is also present on cancer cells that have undergone EMT." (PMID 38634185, 2025). "When VPA decreases E-cadherin and increases vimentin expression, it suggests an EMT-driven transition from a stationary epithelial state to a more migratory and aggressive mesenchymal state, potentially promoting cancer progression and metastasis." (PMID 40283503, 2025). "RM2 and pritumumab bind to vimentin, the same antigen but a different epitope, and both came from a different lymph node which strongly suggests the target, vimentin, is onco-important irrespective of the origin of the cancer type." (PMID 40051499, 2025). "The canonical functions of vimentin in cell mechanics and migration have been recently expanded by the discovery of new roles for extracellular vimentin (ECV) in immune responses to infection, injury and cancer." (PMID 40251523, 2025). "Similarly, 21.8% of vimentin-positive cells were SALL2-positive in normal tissue, whereas only 1% in cancer tissue showed this positivity." (PMID 40869218, 2025). "Further, and vimentin regulates EMT, which can thereby affect cancer metastasis." (PMID 40251523, 2025). "Notably, vimentin is an intermediate filament that is upregulated during epithelial–mesenchymal transition (EMT) and serves as a marker for cancer progression, metastasis, and stem-like cell properties." (PMID 40227834, 2025). "In addition, the nuclear translocation of β-catenin also promotes the upregulation of N-cadherin and vimentin levels, while downregulating E-cadherin, in order to mediate epithelial-mesenchymal transition (EMT) during cancer metastasis." (PMID 40303992, 2025). "Epithelial–mesenchymal transition (EMT) is a key process in CRC progression and metastasis, characterized by the loss of epithelial markers (e.g., E-cadherin) and the gain of mesenchymal markers (e.g., vimentin and ZEB1), enhancing cancer cell migration and invasion." (PMID 40969596, 2025). "Notably, bromodomain PHD-finger TF (BPTF) is an attractive target for certain cancers, considerably correlating with the expression levels of EMT markers (Vimentin and E-cadherin), which can promote EMT progression in CRC." (PMID 40109856, 2025). "Although EMT is partially reactivated in different types of cancer, it often does not reach its full extent in tumor cells, resulting in the lack of end-stage markers such as vimentin." (PMID 40287412, 2025). "Through the modification and regulation of these three signaling pathways, estrogen/androgen, E-cadherin/vimentin, and the PI3K/AKT cascade, PKIB has important cytosolic roles in cancer development, metastasis, and proliferation/evasion of apoptosis, respectively." (PMID 38731883, 2024). "While vimentin, a type III intermediate filament, provides structural and functional support to cells, protects cancer cells from mechanical stress during migration and provide increased plasticity and is considered as a canonical marker of EMT in cancer." (PMID 38737746, 2024). "Additionally, vimentin modulates DNA repair pathways to facilitate EMT and confer cellular resilience against diverse stresses encountered during the process of cancer invasion." (PMID 38667800, 2024). "Although it is unclear whether vimentin is directly involved in heterocellular adhesion, it plays an essential role in CAF-led cancer invasion and metastasis." (PMID 38730588, 2024).
cancer (continued). "E-cadherin, Vimentin, and Twist are epithelial mesenchymal transition (EMT) markers in cancer." (PMID 38783241, 2024). "Similarly, in another study, the expression of EMT markers including vimentin, ZEB1, and ZEB2 increased significantly in the sorafenib-resistant group, resulting in the infiltration of cancer cells into the surrounding liver tissue and the formation of VC." (PMID 38737903, 2024). "ATMSC which uptook either nEV (nEV-ATMSC) or MpEV (MpEV-ATMSC) showed no significant changes in the expression of cancer-associated fibroblast markers (e.g., FAP, FSP, Vimentin)." (PMID 38515582, 2024). "Therefore, the interplay between the RAS/ERK pathway and N-cadherin, vimentin, and E-cadherin, as well as MMP-2 and MMP-9, is crucial for cancer cell proliferation and migration." (PMID 39769029, 2024). "Immunohistochemical (IHC) analysis revealed that the cancer cells were negative for desmin and positive for vimentin." (PMID 38185762, 2024). "Moreover, various reports have shown loss and/or delocalization of E-cadherin and β-catenin expression patterns, in addition to enhanced expression of vimentin to trigger EMT, which further promotes cancer progression." (PMID 38431613, 2024). "These cancer cells were negative for desmin, but positive for vimentin, CK7, and CK19 on immunohistochemical examination." (PMID 38185762, 2024). "The observations support the hypothesis that the dynamic turnover of vimentin filaments and their interacting proteins govern mesenchymal cell migration, EMT, cell invasion, and cancer metastasis." (PMID 39796712, 2024). "For early-stage cancers, DNA methylation-based biomarkers are of particular importance Recent scientific work indicates the high potential of hypermethylated genes TWIST1, VIM, ZNF671, OTX1, and IRF8 for early diagnosis and PTK2, AHNAK, and DAPK for BC prognosis." (PMID 39685620, 2024). "A separate study on the same cancer highlighted UNC5B’s role in cell migration, invasion, and metastasis by interacting with key migration markers such as fibronectin, beta-catenin, and vimentin." (PMID 39456519, 2024). "Once cancer cells arrive in the new soft environment of the lung, they release soft EVs that transform the resident fibroblasts toward a CAF phenotype through increased expression of ACTA2, COL1A1, and VEGFA, VIM." (PMID 38630893, 2024). "In hepatocytes, vimentin is not expressed, except during transformation into cancer cells or during fibrosis." (PMID 39057066, 2024). "Moreover, overexpression of MMP-9 and Vimentin implicates local aggressive behavior of tumors and inhibition of MMP-9 and Vimentin can suppress the migratory and invasive abilities in cancer." (PMID 38554175, 2024). "The authors found that exosomes derived from the MHCC97H cancer line induced human lens epithelial cells (HLE cells) to the EMT process, as evidenced by the higher expression of mesenchymal markers α-SMA and vimentin and the lower expression of epithelial marker E-cadherin than in control HLE cells." (PMID 38473285, 2024). "In addition to its roles in mechanobiology, cell migration, and proliferation, vimentin is a well-used marker of EMT and is frequently used to label cancer cells." (PMID 39057066, 2024). "The ACTA2, VIM, COL3A, COL10A, and MMP11 myCAFs were the dominant CAFs in HGSOC tumors and could induce cancer cell EMT in vitro." (PMID 38525245, 2024). "Further, although vimentin is not usually expressed in carcinomas, poorly differentiated tumors have been reported to express this intermediate filament protein." (PMID 39199675, 2024). "Metastases from the cervix are immunoreactive for CK7, CEA, and p16 and are negative for ER and vimentin, and disseminations from carcinoma of the endometrium and ovary are positive for paired-box gene 8 (PAX8) and negative for CK20 and CDX2." (PMID 38674171, 2024).
cancer (continued). "Furthermore, epithelial-to-mesenchymal transition (EMT), a critical step in the invasion and metastasis of various cancers characterized by low expression of E-cadherin and high expression of the EMT-induced markers N-cadherin and vimentin, was evaluated." (PMID 37739958, 2023). "MB49 cancer cells exposed to TGF-β1 exhibited increased migration, invasiveness and upregulation of epithelial-mesenchymal transition markers α-Smooth Muscle Actin and Vimentin." (PMID 36761730, 2023). "The expression of Cx37, Cx40, Panx-1, and vimentin differed significantly between the epithelium of normal laryngeal mucosa and the atypical epithelial cells of LSCC and was related to the histological grade and biological behavior of the cancer." (PMID 36833374, 2023). "Histopathological analysis confirmed the diagnosis of poorly differentiated invasive malignant neoplasms, which were further classified as carcinomatosis based on positive cytokeratin and negative vimentin immunohistochemistry results." (PMID 38105775, 2023). "Vimentin, also known as fibroblast intermediate filament, is the major intermediate filament found in non-muscle cells and cancer cells." (PMID 37099541, 2023). "Besides, USP10 has been shown to be involved in cancer cell migration by regulating the stability of the EMT-transcription factor Slug/SNAI2 and Vimentin." (PMID 37919637, 2023). "Conversely, in both priPC-1 primary cancer cells and established PANC-1 cells, shRNA-mediated knockdown or CRISPR/Cas9-induced knockout of MXRA5 exerted opposite functions by upregulating E-Cadherin, but downregulating N-Cadherin and vimentin." (PMID 36828810, 2023). "Also, the CAF secretome improves the expression of vimentin, ZEB1, and Snail in cancer cells, which are mesenchymal proteins essential for cancer progression." (PMID 37834441, 2023). "Western blotting results revealed that TMZ-resistant U87MG-R cells highly expressed CYBB along with Nrf2, SOD2, and other epithelial–mesenchymal transition (EMT) markers, such as slug, vimentin, N-Cadherin, and CD44, in addition to the upregulation of cancer stemness marker CD133." (PMID 37175412, 2023). "The MI CECs exhibited a range of vimentin expression comparable to the non-altered cells found in cancer patients." (PMID 37568766, 2023). "According on the results of observations and statistical analysis, it was found that the number of cells expressing vimentin, MMP1, and PDGF in ductal type cancers was different from the lobular type cases that underwent local recurrence after mastectomy and adjuvant chemotherapy." (PMID 38046195, 2023). "However, the CM-DOP treatment reversed the effects of N-cadherin and Vimentin, as well as increased the E-cadherin expression in AGS and HGC-27 cancer cells, especially in H-DOP." (PMID 37894541, 2023). "In the EMT of cancer tissues, it was found that overexpressed SNHG5 increased the expression of epithelial-related marker E-cadherin while decreasing the expression of mesenchymal-related markers vimentin and N-cadherin, as well as transcription factors." (PMID 36711024, 2023). "In some in vitro cancer models, such as melanoma, cervical carcinoma, and breast cancer, the role of EMT markers (i.e., N-cadherin, Vimentin, Snail, and Twist) as promoters of cell motility and increased resistance to an anti-cancer treatment has been described." (PMID 38255193, 2023). "By causing cell divisions, increasing cell motility, and stimulating the expression of genes including vascular endothelial growth factor (VEGF), hypoxia-inducible factors (HIF-1), vimentin (VIM), and REL proto-oncogene, NF-kB subunit (REL), Ang1-9 appears to have pro-cancer effects." (PMID 37891636, 2023). "The lack of vimentin significantly inhibits the migration and deep invasion of cancer cells, whereas its expression is positively correlated with a longer persistence time of migration." (PMID 38132928, 2023).
cancer (continued). "However, six proteins influenced cancer cell survival in the COS–GA group in previous studies, with downregulated HSPA9 and HIST2H2BF and upregulated KRT18, HINT1, DSP, and VIM proteins." (PMID 37371778, 2023). "In contrast to vimentin, the possible involvement of Cxs and Panxs in LSCC progression remains unexplored, and the elucidation of their control mechanisms offers an opportunity to target cancer behavior." (PMID 36833374, 2023). "The mechanism of MEP1A promoting cancer development may be realized by changing the expression of MMP9, vimentin, and E-cadherin, and participating in the EMT procession." (PMID 37100777, 2023). "As EMT is a common process that has been postulated to be responsible for carcinoma cell metastasis, the effect of the BCSC secretome on the expression of epithelial markers (CDH1, TJP1 and OCLN) and mesenchymal markers (Snail, FN1, MMP2 and VIM) was assessed." (PMID 36915147, 2023). "As a general feature, the expression of epithelial genes (e.g. TJP3, TSPAN13, CLDN7 and EPCAM) was positively correlated with the expression of AGR2/3 and the expression of mesenchymal genes (e.g. VIM and MSN) was negatively correlated, with specific correlations according to cancer type." (PMID 35857928, 2022). "In addition, we analyzed the correlation pair-wise (Pearson’s correlation test), between PEBP1 (RKIP) and SNAI1, VIM, CDH1/2, EPCAM, and LAMA1/B1 genes, across the 22 different types of cancer and normal tissues in the TCGA database." (PMID 36230521, 2022). "VEGF-overexpressing cancer cells show increased tumorigenicity, invasiveness, proliferation, and EMT characteristics, including mesenchymal marker expression (N-cadherin, Snail2, and vimentin)." (PMID 36358584, 2022). "Finally, by considering the genes recapitulating IL-3 biological functions, we proposed a model, including IL-3Rα, SNAI1, ZEB1, VIM, CTNNB1, MMP2, SPRY2, and CD274, that remarkably discriminates cancer aggressiveness (AUC = 0.86 95% CI = 0.82–0.89)." (PMID 36010912, 2022). "Evaluated levels of ROS may contribute to activating NF-κB signaling, which increases IL-6 production by cancer cells and CAFs, thus facilitating the EMT program by regulating the expression of N-cadherin, E-cadherin, vimentin, Twist and Snail." (PMID 35251963, 2022). "EMT is a dynamic process in cancer cells, and factors released by TAMs or immune cells in the TME can promote EMT and changes of expression in a variety of molecules, such as E-cadherin, N-cadherin and vimentin." (PMID 35457057, 2022). "Vimentin is highly expressed in carcinoma cells that undergo EMT, and new drugs targeting vimentin might lead to improvements in cancer therapy." (PMID 36669020, 2022). "VIM, LGALS1, SERPINE1, PKP3 and the CDH1‐CDH2 switch were consistently altered in all the EMT models and have all been related to EMT in different cancer types." (PMID 34942055, 2022). "Likewise, low expression levels of CDH1 and high expression levels of VIM and ACTA2 in cancer cells indicate the high metastatic potential of cancers and correlate with the poor prognosis of affected patients." (PMID 35621926, 2022). "Our group has previously reported that a substantial proportion of CTCs in cancer patients may express stem cell and EMT markers, such as aldehyde dehydrogenase 1 (ALDH1), twist, and vimentin (VIM)." (PMID 35326725, 2022). "Vimentin and E-cadherin are important markers of EMT in cancer metastasis." (PMID 35770085, 2022). "Cancer cells in the recurrence displayed a phenotype of epithelial–mesenchymal transition (EMT), as evidenced by increased expression of mesenchymal proteins CD44 and vimentin." (PMID 35692807, 2022). "Vimentin expression is an independent factor in the short postoperative prognosis of PDAC, which indicates that, similar to PDAC cell lines, human PDAC cases contain epithelial or mesenchymal cancer cell types." (PMID 35629168, 2022).